RN7SKP152 (RN7SK pseudogene 152)
Gene: Miscellaneous RNA gene on chromosome 2 (166,180,652 to 166,180,966, reverse strand). Ensembl gene ENSG00000222376.
Homologues: Orthologues: chimpanzee 7SK (94% identical). Paralogues in human: RN7SKP93 (68% identical), RN7SKP102 (68% identical), 7SK (67% identical), RN7SKP204 (66% identical), RN7SKP255 (66% identical), RN7SKP47 (66% identical), RN7SKP71 (66% identical), RN7SKP9 (66% identical), RN7SKP170 (66% identical), RN7SKP246 (66% identical), RN7SKP20 (65% identical), RN7SKP250 (65% identical), and 284 more.